IL6 (interleukin 6)
Diseases named in the same sentence as IL6 in open-access papers (continued):
Sharing a sentence is not in itself a finding about the gene and the disease.
tumor (continued). "Inflammatory cytokines such as IL-1, IL-6, and IL-8 may be induced by monocytes and macrophages recruited by the tumor, and may regulate cancer stem cell self-renewal in their niches." (PMID 27901106, 2016). "In cancer, IL-6 activates target genes involved in a number of biological activities such as differentiation, survival, apoptosis, and proliferation and also modulates tumor cell migration and progression." (PMID 27851822, 2016). "Interleukin-6 is one of the most well-characterized pro-inflammatory cytokines found in tumors and has been shown to drive tumor growth and proliferation, stimulate angiogenesis, lead to chemoresistance, promote epithelial-to-mesenchymal transition, and increase the rate of metastasis." (PMID 27531896, 2016). "We showed that IL-6 treatment led to a decrease in caspase 3/7 activity in the tumor cells." (PMID 27340780, 2016). "Interestingly, a blockade of IL-6 secreted from MDSCs has been reported to support the anti-tumour immunity." (PMID 27211851, 2016). "Since IL-6 is also known to enhance secretion of several chemokines/cytokines in tumor cells, we examined whether some of the effects of IL-17 were mediated indirectly via enhancement of IL-6 secretion." (PMID 26755664, 2016). "It was reported that IL-1β and IL-6 stimulate glucose metabolism and promote tumour progression." (PMID 26869854, 2016). "Considering that IL-6 secreted by irradiation from DCs and tumor cells may affect DCs through autocrine and paracrine signaling, we investigated whether IL-6 could hinder IL-12 production in DCs." (PMID 26745884, 2016). "The IL-6 signaling axis is commonly upregulated in invasive cancers, suggesting that IL-6 may be an important mediator of events involved in tumor cell invasion." (PMID 26268945, 2015). "Indeed, inflammatory cytokines like IL-6 and other chemokines like IL-8 are upregulated in the supernatant of Amela compared to Mela tumor cells." (PMID 25853464, 2015). "To determine whether circulating IL-6 influences the ability of CD4+ T cells to control tumours, we employed IL-6 blockade combined with OT-II cell transfer." (PMID 25850032, 2015). "In addition, IL-16 can activate the secretion of tumor-associated inflammatory cytokines, such as TNF-α, IL-1β, IL-6, and IL-15, all of which are major factors involved in tumorigenesis." (PMID 25954818, 2015). "When the IL-6 immunohistochemical scores of matched normal and cancer tissues were compared, we observed higher levels of the IL-6 expression in seventy-five percent of tumor tissues." (PMID 26282935, 2015). "Similar to the effects seen in BMDMs, peritoneal macrophages from 4T1 tumor-bearing mice exhibited significantly strengthened production of IL-6 and moderately increased production of CCL2 and TNFα in response to LPS when compared to macrophages from control mice." (PMID 26177198, 2015). "We observed IL-6 is highly expressed in HCC tumor tissue compared with normal liver tissue." (PMID 26376676, 2015). "As CSC-like cells can arise de novo from non-tumorigenic cells or following induction as a result of IL-6 secretion by CSCs, a dynamic equilibrium between CSCs and non-CSCs is suggested to exist in order to maintain a constant proportion of tumor-propagating cells over successive generations." (PMID 25595909, 2015). "The results of this study compared with the present study suggest that IL-6 is a more specific cytokine in laryngeal malignancies, levels of which increase considerably both compared with normal subjects and in advanced stages of tumor." (PMID 26082901, 2015). "The IL-6/Janus kinase (JAK)/Signal transducer and activator of transcription (STAT) 3 pathway is one of the most important signaling pathways associated with tumour development and induction of tumour induced immune suppression." (PMID 25669986, 2015). "IL6 expression was found mainly in the intraseptal regions of tumor sections." (PMID 26215971, 2015).
tumor (continued). "Similarly, for the hepatic RFA / nano anti-IL6 siRNA at Day 0, the tumor proliferative index at 7d was significantly lower compared to Day 3 administration (p = 0.001)." (PMID 26154425, 2015). "Both autocrine and paracrine IL-6 signaling induced tumor aggressiveness." (PMID 26258407, 2015). "IL-6 is an established osteolytic factor, promoting bone resorption by a variety of mechanisms, including direct activation of osteoclasts and stimulation of osteolytic factor release from tumor and stromal cells within bone tissue." (PMID 25714031, 2015). "In this study, in CT26 and 4T1 cells, we found that GZMM is positively related to IL-6 and VEGF release, which indicates that GZMM may be involved in tumor-associated inflammatory response and angiogenesis." (PMID 25788270, 2015). "In conclusion, our findings showed that PGE2 modulates the growth of EAT and that inhibition of tumor growth could be partly related to suppression of the release of IL-6 and to stimulation of the release of IL-13." (PMID 26347589, 2015). "It was hypothesized that IL-6 upregulated in aged mice altered the cytokine production by tumour-specific CD4+ T cells to prevent them from attacking the tumours." (PMID 25850032, 2015). "The patients with elevated serum IL-6 concentration may benefit from more frequent recall visits for the purpose of early diagnosis of tumour recurrence." (PMID 25858079, 2015). "IL-6 levels increased significantly with increasing local tumor spread only (Table." (PMID 26082901, 2015). "Because there are many cytokines in the tumor microenvironment, including IL-4, IL-6, IL-10, and IL-13, we next asked whether these cytokines down-regulated miR-146a and miR-222 in late tumor TAMs." (PMID 26689540, 2015). "The Fas signaling has also been demonstrated to promote IL-6 secretion in tumor cells." (PMID 25992623, 2015). "Since the TERT protein is proposed to co-activate NFκB to enhance gene-expression of e.g IL-6, TNFα and other pro-inflammatory cytokines, contributing to tumor progression, we analyzed the relative mRNA levels on thirty-six AML patients with different rs2853669 genotypes." (PMID 26298771, 2015). "MDSCs represent a diverse population of immature and highly immunosuppressive myeloid cells that accumulate in the tumor, blood, lymph nodes, and bone marrow of tumor-bearing hosts in response to tumor-derived factors, such as IL-6, IL-10, PGE2, TGF-β2, and VEGF." (PMID 26217588, 2015). "In addition to increasing cell migration and invasion, ectopic S100A9 expression in tumor cells promoted xenograft tumorigenesis as well as the dominant expression of myeloid cell markers and pro-inflammatory IL-6." (PMID 26315114, 2015). "However, the depletion of CD8+ T cells abrogated this antitumour effect, suggesting that therapeutic effect of tumour-specific CD4+ T cells in IL-6-neutralized aged mice was mediated through CD8+ T cells." (PMID 25850032, 2015). "Another report proposed that MSC-secreted IL-6 may enrich the pro-angiogenic factors secreted by cancer cells to increase angiogenesis and tumor growth, and targeting this interaction may lead to novel therapeutic and preventive strategies." (PMID 25986392, 2015). "We recently reported that gankyrin could promote CCA tumor growth and metastasis through activation of IL-6/STAT3 signaling." (PMID 26015398, 2015). "Adjuvant MNP anti-IL6 siRNA suppressed the thermal ablation-induced effects on distant R3230 tumor growth such that the mean tumor size at 7d with combination therapy was lower than either the sham (non-ablation) and hepatic RFA alone groups (p = 0.02 vs. sham, p<0.001 vs. hepatic RFA alone)." (PMID 26154425, 2015). "IL-6 might drive STAT3 expression in tumour cells, induce angiogenesis and epithelial-mesenchymal transition and induce differentiation of dendritic cells and macrophages toward tumour promoting cells." (PMID 25889974, 2015).
tumor (continued). "Additionally, numerous soluble mediators, including TNF-α, TGF-α, TGF-β, IL-1β, IL-1α, IL-6, IL-8, VEGF, and others have been implicated in PC carcinogenesis, tumor progression, and treatment resistance." (PMID 26498838, 2015). "Similarly, RF ablation of normal kidney increased distant R3230 tumor growth compared to sham treatment that was also suppressed with single-dose adjuvant MNP anti-IL6 siRNA (given at Day 0)." (PMID 26154425, 2015). "We found that a subgroup of ES tumors strongly expressed IL6 in the tumor connective tissue septa." (PMID 26215971, 2015). "In our study, we showed that estrogen suppressed production of IL-6 and subsequently reduced W4P-induced tumor growth in male mice, which suggests that a high level of estrogen in female mice suppresses tumorigenesis by W4P variant HBV through regulating IL-6 signaling." (PMID 25645622, 2015). "Taken together with our evidence that IL6 intracellular signalling may induce MaSC-like properties, these findings suggest that tumour cell-derived IL6 is a major mediator of CSC properties." (PMID 26671411, 2015). "Here, we confirm recent reports that thermal ablation of normal organ parenchyma (such as liver or kidney) can stimulate distant tumor growth in at least two different tumor models, and further demonstrate that this in part due to ablation-induced increases in IL-6." (PMID 26154425, 2015). "Of these effectors, MCP-1 likely concentrates monocytes and neutrophils at the tumor site, provoking an inflammatory response; IL-6 and IL-12, which are responsible for activation of T- and B-cells, would facilitate production of tumor cell-specific antibodies." (PMID 26006716, 2015). "More interestingly, we also observed the fact that icaritin could decrease effectively the levels of serum IL-6 and IgE in the tumor-bearing mice." (PMID 25865044, 2015). "Up-regulation of IL-6 has been reported to enhance the migration ability of various tumor cells." (PMID 26513016, 2015). "Moreover, at the tumor site, the IL-1 and IL-6 cytokines, the S100A8 and S100A9 pro-inflammatory proteins, the chemo-attractant molecules CCL2, SDF1 and CXCL5 are the main factors responsible for the recruitment and the induction of MDSCs." (PMID 28536400, 2015). "Immunohistochemistry proved IL6 expression in the stroma of ES tumor samples." (PMID 26215971, 2015). "STAT3 and NF-κB could be activated by IL-6 to prevent apoptosis and promote proliferation of malignant tumor cells." (PMID 25934640, 2015). "Accordingly, levels of MCP-1 and IL-6 were elevated in the serum of tumor-bearing hosts." (PMID 26172047, 2015). "In addition to its potential role in tumor promotion and progression, overexpression of IL-6 has been suggested to promote resistance to EGFR TKIs in both EGFR-dependent and EGFR-independent manners." (PMID 26513016, 2015). "In our model, a2NTD treatment stimulates neutrophils to secrete enhanced amount of TNFα, IL-1 and IL-6 suggesting that neutrophils in the site of the tumor may be a potential source of these mediators." (PMID 26460736, 2015). "Whether hCG could drive collaboration between tumor cells and macrophages in the production of IL-6 and consequent chemoresistance was assessed." (PMID 26608647, 2015). "Presently, it is unclear whether inhibition of IL-6 signaling by for example blocking AP-1 and/or NF-κB is beneficial or detrimental to tumor response." (PMID 26516076, 2015). "Thus, IL-6 exerts anti-apoptotic effects while concomitantly downmodulating anti-tumor immune memory." (PMID 26307977, 2015). "Although our results have shown that serum IL-6 concentration was higher in men than women, sex was not significant risk factor for tumour recurrence as was shown by other authors." (PMID 25858079, 2015).
tumor (continued). "It is interesting to note that the in vitro enhancement of LPS-induced IL-6 and TNFα production seemed to be a transient effect which faded over 72 h, although peritoneal macrophages from 4T1 tumor-bearing mice also exhibited increased production of pro-inflammatory cytokines." (PMID 26177198, 2015). "Moreover, we identified IL-6 expression status of EOC tumor as an independent predictive biomarker for ascites formation in patients receiving adjuvant carbotaxol treatment." (PMID 26282935, 2015). "In addition, in B16 melanoma and MB49 bladder carcinoma models, IL-17 induced IL-6 production by tumor cells which, in turn, activated Stat3-dependent survival and angiogenic genes expression." (PMID 26583099, 2015). "Third, by RT-qPCR analyses, TANs showed downregulation of anti-tumor genes (e.g., il4, il6, il8, il10, il12, and tnfa) and upregulation of pro-tumor genes such as il1b, which also promotes early cancer angiogenesis, indicating a potential role of TANs in pro-angiogenesis in HCC initiation." (PMID 25828472, 2015). "However, IL-6 can also be secreted from several cell types comprising the tumor microenvironment such as macrophages, endothelial cells, and cancer fibroblasts, so the paracrine role of IL-6 will also be important." (PMID 26313152, 2015). "In addition, PGE2 and IL-6 signal pathways are involved in the cross talk between tumor and stromal cells." (PMID 26347589, 2015). "Plasma IL-6 levels were elevated in all tumor bearing mice but was greatest in group β mice." (PMID 25709898, 2015). "IL-6 expression was similar in wild type and Shb +/− total tumor RNA." (PMID 25885274, 2015). "However, IL-6 was also found to inhibit immunogenic tumor growth by stimulating antitumor T-cell activity." (PMID 26684834, 2015). "Therefore, heightened IL-6 appeared to act predominantly on tumour-specific CD4+ T cells in aged mice." (PMID 25850032, 2015). "While the secretion of these cytokines from the primary tumor undoubtedly plays a role in metastatic progression, our observations strongly suggest that priming of distal macrophages can result in secondary production of TNFα, IL-6, and CCL2." (PMID 26177198, 2015). "This increase could be due to the elevated IL-6 release by the untreated NK cells, by OSCSCs or both after NK-tumor interaction and cross-signaling." (PMID 25860927, 2015). "This discrepancy may be due to differences in gene expression between tissue and cells, differences in IL-6 expression with tumor grade/invasiveness, degree of “stemness” in cell lines vs. tissue, and differences between the assays and/or sample collection." (PMID 26268945, 2015). "Conversely, NOX4 shRNA-transfected A549 cells produced smaller tumors compared with scramble, and additional IL-6 administration could significantly rescue tumor growth." (PMID 25504436, 2015). "Moreover, adjuvant MNP anti-IL6- siRNA suppressed increased distant tumor growth and Ki-67 observed in R3230 and MATBIII tumors post hepatic RFA (p<0.01)." (PMID 26154425, 2015). "IL-6 has been proposed to enhance cell proliferation and metastatic ability of tumor cells." (PMID 26513016, 2015). "IL6 has a wide range of tumor promoting activities in a large variety of cancer cells." (PMID 26215971, 2015). "Considering the well-known anti-angiogenic effect of IL-6 inhibition, and our own results demonstrating that tocilizumab inhibited tumor angiogenesis, it is possible that the anti-tumor effect of tocilizumab is mediated, at least in part, by decreased supply of oxygen and nutrients to tumor cells." (PMID 26287605, 2015). "Either PDTC or IL-6 neutralizing antibody treatment could repress sunitinib-induced tumor cell self-renewal and CSC marker expression." (PMID 25675297, 2015). "IL-6 has been shown to be important for the number and size of tumours formed in mice, and IKKβ conditional knockout mice have been shown to develop more numerous tumours." (PMID 25625467, 2015).
tumor (continued). "Although other potential mechanisms that mediate the Loxoribin-mediated anti-tumor effects cannot be excluded, our results suggest that IL-6 produced by Loxoribin-treated DCs in the co-culture system is largely responsible for the reversal of Treg-mediated suppression." (PMID 25593198, 2015). "The genetic signature derived from non-tumor liver tissue may reflect the promoting effects of IL-6 on the development of metachronous tumors that are independent from the primary resected HCC." (PMID 26525581, 2015). "Importantly, prevailing among all the different molecules that were identified in the co-culture of the three cell types was CCL2, followed by IP-10 (CXCL10) and IL-6, confirming the central role of these molecules in this tumor model." (PMID 25599228, 2015). "Therefore, we next evaluated human breast CAFs to determine their contribution of IL-6 in the tumor microenvironment." (PMID 26268945, 2015). "In addition to fibroblast, IL-6 secreted from other stromal cell types such as adipose cells, can promote migration and invasion of tumor cells such as breast cancer." (PMID 26501341, 2015). "Furthermore, a tumor-induced decrease in spontaneous locomotor activity was correlated with the systemic levels of IL-6 in mice." (PMID 26546348, 2015). "It has been reported that IL-6 promotes tumor cell migration and invasion, and that ROCK1 may be involved in this process." (PMID 25723491, 2015). "In addition, we observed an increase in IL-6Rα levels in tumour cells and soluble IL-6R serum levels as well as increased Stat3, IL-6Rα and IL-6 mRNA levels in Ptenpc−/− PCa compared with WT controls." (PMID 26198641, 2015). "Moreover, cancer cells, tumor-derived fibroblasts, and antigen-presenting cells secrete several key cytokines for Th17 differentiation such as IL-1β, IL-6, IL-23, and TGF-β." (PMID 26583099, 2015). "Interestingly, in most studies, the pro-inflammatory and tumor-promoting activity of IL-6 was mediated via IL-6 trans-signaling." (PMID 26673628, 2015). "In addition, the treatment of EAT-bearing mice with indomethacin has stimulated the IL-13 production and has significantly inhibited IL-6 in the 13th day of tumor growth." (PMID 26347589, 2015). "IL-6 inhibits tumor growth by blocking the cell cycle in the G1 phase." (PMID 25785244, 2015). "The pro-inflammatory factor IL-8 appeared to be made primarily by the tumor and while IL-6 was released by both immune cells and tumor, its levels were more uniform and robust in reconstituted animals bearing PC3 tumors, again suggestive of an immune cell-tumor interaction." (PMID 25901284, 2015). "In general, IL-6 in cancers is associated with proliferation, inhibition of apoptosis, carcinogenesis and conversion of non-cancer cells into tumour stem cells." (PMID 25902944, 2015). "Further analysis of excised intestinal polyps showed that the adoptive transfer of Apc HET Tregs reduced the levels of proinflammatory mediators IL-6, IL-1β, and IL-23 in the tumor microenvironment compared with wild type intestinal tissue but the expression level of TNF was not decreased." (PMID 26146642, 2015). "In addition, various studies have revealed that IL-6 is one of the adverse prognostic factors for cancer progression and has tumour-promoting effects." (PMID 25850032, 2015). "Accordingly, PDT-induced IL-6 signaling in the tumor microenvironment might contribute to an anti-tumor innate and adaptive immune response while restraining angiogenesis." (PMID 26307977, 2015). "Taken together, in addition to the negative impact on Th1 differentiation, this cytokine circuit could be another mechanistic feature of IL-6 in converting the function of IL-21 from immunostimulatory to tolerogenic for tumour outgrowth in aged animals." (PMID 25850032, 2015). "While IL-6 may facilitate tumor cell survival and ameliorate the anti-tumor adaptive immune response, it seems to deter tumor cell proliferation, which is beneficial for PDT outcome." (PMID 26307977, 2015).